PSORS1C1 (psoriasis susceptibility 1 candidate 1)
Synonyms: C6orf16; SEEK1
Tractability: No criterion of Open Targets' tractability assessment is met for any kind of drug.
Safety:
Unwanted effects reported when the protein is acted on. In parentheses: how it was acted on, where the effect was seen, and who reports it.
DRESS Syndrome or Stevens-Johnson Syndrome (source: ClinPGx)
severe cutaneous adverse reactions (source: ClinPGx)
severe cutaneous adverse reactions (SCAR) (source: ClinPGx)
thrombocytopenia (source: ClinPGx)
Gene: Protein-coding gene on chromosome 6 (31,114,750 to 31,140,092, forward strand). Ensembl gene ENSG00000204540.
Subcellular location (Human Protein Atlas): Nucleoplasm
Genetic constraint (gnomAD): Loss-of-function variants: 5 observed, 9.32 expected, observed/expected ratio (o/e) 0.54, 90% interval 0.28 to 1.13. That is too few expected variants to judge how well the gene tolerates losing a copy. Missense variants: 146 observed, 185.26 expected, observed/expected ratio (o/e) 0.79, 90% interval 0.69 to 0.9. Synonymous variants: 62 observed, 73.26 expected, observed/expected ratio (o/e) 0.85, 90% interval 0.69 to 1.05.
Homologues: Orthologues: chimpanzee PSORS1C1 (97% identical).
Diseases named in the same sentence as PSORS1C1 in open-access papers:
PSORS1C1 is named in the same sentence as 32 diseases in open-access papers, as found by Europe PMC text mining. Sharing a sentence is not in itself a finding about the gene and the disease. The quoted sentences say what the papers report.
psoriasis (23 papers, 2009 to 2024). An autoimmune condition characterized by red, well-delineated plaques with silvery scales that are usually on the extensor surfaces and scalp. "Another gene in common is PSORS1C1 known to confer susceptibility to psoriasis and systemic sclerosis." (PMID 37924108, 2023). "Many studies have confirmed PSORS1C1 on chromosome 6p21.3 to be a major locus for psoriasis susceptibility." (PMID 36078103, 2022). "The SNP conferring the strongest risk, rs3815087, lies in the 5′UTR region of the psoriasis susceptibility 1 candidate 1 (PSORS1C1) gene." (PMID 36078103, 2022). "For the ADO group, rs3130573 [P(T) = 1.70E-10] was located in PSORS1C1 (MIM: 613525) gene which was a major susceptibility locus for psoriasis." (PMID 31024629, 2019). "Meanwhile, there is a pseudogene XXbac-BPG299F13.15 which is located in the same LD region as HLA-C and is interacting with 4 other literature reported psoriasis-associated genes (PSORS1C1, MICA, HCP5, HLA-C)." (PMID 30315195, 2018). "Psoriasis susceptibility 1 candidate 1 (PSORS1C1) gene was initially recognized as it confers susceptibility to psoriasis and psoriatic arthritis." (PMID 30069262, 2018). "Of the differentially methylated loci, PSORS1C1, a susceptibility gene for psoriasis, stood out as an interesting case." (PMID 29387007, 2017). "PSORS1C1 gene is one of psoriasis susceptibility loci, but it is also associated with systemic sclerosis and has been suggested to play an important role in the development of RA." (PMID 25369137, 2014). "SNP rs2517485 is about 10 kb from the putative psoriasis and systemic sclerosis disease susceptibility gene (SEEK1 or PSORS1C1) and the Corneodesmosin Precursor gene (CDSN)." (PMID 22615847, 2012). "rs1265048 falls near CDSN and PSORS1C1 both of which have previously been associated with susceptibility to psoriasis." (PMID 20041220, 2009). "We found few SNPs in exon 2 of CDSN overlapping with PSORS1C1, which can give rise to missense variants strongly impacting on corneocyte adhesion and skin desquamation, as well as associating with increased risk of psoriasis severity." (PMID 38495872, 2024). "rs3815087 lies in the 5′UTR region of the psoriasis susceptibility 1 candidate 1 (PSORS1C1) gene, which further suggests that inflammatory processes might be an important common pathogenic pathway leading to both schizophrenia and psoriasis." (PMID 36078103, 2022). "Significantly, PSORS1C1, a gene linked to psoriasis susceptibility, was also upregulated." (PMID 34769520, 2021). "Moreover, less than 25 kb from this gene, two single nucleotide polymorphisms (SNPs) in the SEEK1 (PSORS1C1) gene retained association with psoriasis upon stratification for HLA-Cw*0602 status (positive/negative)." (PMID 19680446, 2009). "In conclusion, our results demonstrated that rs10484554, rs887466 and rs1062470 genetic variants within the PSORS1 locus encompassing the multiple genes LOC105375015, PSORS1C3 and PSORS1C1/CDSN, respectively, are significantly associated with psoriasis." (PMID 35626191, 2022). "The PSORS1C1 gene, located 127 kb telomeric to the HLA-C locus, is considered to be one of the potential candidate genes for psoriasis." (PMID 36078103, 2022). "It is, thus, not surprising that the variant rs2233945, localized in the same PSORS1C1 gene, modulates the response to etanercept, a TNF inhibitor used for psoriasis and other autoimmune disorders, including rheumatoid arthritis." (PMID 36077453, 2022). "Other genes, such as IL23R, PSORS1C1, HCP5, were found to be associated with psoriasis and rheumatoid arthritis." (PMID 25369137, 2014). "Although the PSORS1C1 gene is located within the PSORS1 locus and is considered one of the potential psoriasis susceptibility genes, the function of its gene product remains unclear in this disease." (PMID 35626191, 2022).
psoriasis (continued). "The locus associated with total WBC count on chromosome 6p21 contains genes associated with follicular lymphoma (CHCG22), progression of HIV-1 infection (CDSN, PSORS1C1 and PSORS1C2) and psoriasis (CCHCR1, PSORS1C1 and PSORS1C2)." (PMID 21738480, 2011).
rheumatoid arthritis (10 papers, 2014 to 2023). A chronic, systemic autoimmune disorder characterized by inflammation in the synovial membranes and articular surfaces. "Recently, it has been reported that the single nucleotide polymorphisms (SNPs) of STAT4, PTPN2, PSORS1C1, and TRAF3IP2RA genes are associated with the clinical efficacy of tumor necrosis factor (TNF) inhibitors in the treatment of rheumatoid arthritis (RA) patients." (PMID 31709198, 2019). "Previous researches revealed a significant increase in expression of PSORS1C1 in rheumatoid arthritis (RA) synovial tissues, indicating that PSORS1C1 might play an important role in the development of RA." (PMID 29387007, 2017).
systemic sclerosis (5 papers, 2011 to 2024). A chronic disorder, possibly autoimmune, marked by excessive production of collagen which results in hardening and thickening of body tissues. "One study reported that PSORS1C1 was associated with HLA–independent systemic sclerosis." (PMID 30662464, 2018).
schizophrenia (3 papers, 2017 to 2022). A major psychotic disorder characterized by abnormalities in the perception or expression of reality. "For five loci shared between openness and schizophrenia (BRINP2, SDCCAG8, PSORS1C1, DGKI and AK093940), the effect directions were concordant." (PMID 28533504, 2017). "Due to the intricate LD in this region, we consider this conjunctional hit as to reflect the involvement of MHC in both schizophrenia and openness rather than PSORS1C1 specifically." (PMID 28533504, 2017).
Arthritis (2 papers, 2019 to 2022). Inflammation of a joint. "Finally, our results suggest that PSORS1C1 gene under-expression might be in psoriatic patients free from arthritis." (PMID 35626191, 2022).
gout (2 papers, 2019 to 2025). A condition characterized by painful swelling of the joints, which is caused by deposition of urate crystals. "This is the first study to identify the allele and genotype frequencies of HLA-B*58:01 using the Sanger sequencing method and to investigate its association with paraclinical characteristics and the SNP rs9263726 of the PSORS1C1 gene in randomly selected gout patients living in Northeast Vietnam." (PMID 40870966, 2025). "HLA-B*58:01 was not consistently associated with the SNP rs9263726 of the PSORS1C1 gene, suggesting that rs9263726 may not be a reliable surrogate marker for HLA-B*58:01 in gout patients." (PMID 40870966, 2025).
acne rosacea (1 paper, 2025). "However, the risk allele substantially enhances TFAP2A DNA binding, consistent with a model in which the rs1264326 daSNV enhances TFAP2A promoter binding to alter expression of DDR1 and PSORS1C1 pro-inflammatory genes and drive risk for acne rosacea." (PMID 40998781, 2025).
AIDS (1 paper, 2011). A syndrome resulting from the acquired deficiency of cellular immunity caused by the human immunodeficiency virus (HIV). "The role of the protein product of PSORS1C1 is presently unknown, although one SNP in PSORS1C1 immediately downstream the region we analysed has been associated through GWAS with white blood cell counts and a second downstream variant with delayed AIDS progression." (PMID 21682861, 2011).
chronic obstructive pulmonary disease (1 paper, 2020). A chronic and progressive lung disorder characterized by the loss of elasticity of the bronchial tree and the air sacs, destruction of the air sacs wall, thickening of the bronchial wall, and mucous accumulation in the bronchial tree. "Elevated sputum PSORS1C1 (Psoriasis Susceptibility 1 Candidate 1) levels have been shown in chronic obstructive pulmonary disease (COPD)." (PMID 33133517, 2020).
hypotrichosis (1 paper, 2020). A congenital condition, usually due to genetic aberrations, that is characterized by a lack of hair growth on the head and/or body. "Although the deletion encompasses several other genes (C6orf15, PSORS1C1, PSORS1C2, CCHCR1 and part of TCF19), these patients show a phenotype resembling that of PSD without hypotrichosis." (PMID 31663161, 2020).
leprosy (1 paper, 2020). Leprosy is a chronic infectious disease affecting primarily the skin and peripheral nervous system. "The third SNP, rs1265048, is located near the C6orf15 (1.07 kb), PSORS1C1 (1.12 kb), and CDSN (1.2 kb) genes and it gave a univariate p-value of 5.5x10-11 in the combined analysis, with an OR for developing leprosy for CT vs. TT (or CC vs. CT) of 0.69 [0.58–0.80]." (PMID 32421744, 2020).
lung carcinoma (1 paper, 2024). "For example, HLA-L showed strong evidence of association with lung cancer, PSORS1C1 was implicated in adenocarcinoma at the gastroesophageal junction." (PMID 38461317, 2024).
tumor (1 paper, 2018). "Downregulation of PSORS1C1 was observed in the tumor tissues while STARD3 and NM23 gene expression increased, when compared with the adjacent normal tissues." (PMID 30662464, 2018).
PSORS1C1 also shares sentences with these, for which no sentence is quoted: adenocarcinoma (1 paper); ankylosing spondylitis (1); asthma (1); autoimmune disease (1); autoimmune disorders (1); cardiomyopathy (1); COVID-19 (1); deficiencies (1); follicular lymphoma (1); heart failure (1); HIV-1 infection (1); inflammation (1); major depressive disorder (1); psoriatic arthritis (1); sarcoidosis (1); sarcopenia (1); squamous cell carcinoma (1); systemic lupus erythematosus (1); thyroid diseases (1).